SLC1A5 (solute carrier family 1 member 5)
Description:
Sodium-coupled antiporter of neutral amino acids. In a tri-substrate transport cycle, exchanges neutral amino acids between the extracellular and intracellular compartments, coupled to the inward cotransport of at least one sodium ion. The preferred substrate is the essential amino acid L-glutamine, a precursor for biosynthesis of proteins, nucleotides and amine sugars as well as an alternative fuel for mitochondrial oxidative phosphorylation. Exchanges L-glutamine with other neutral amino acids such as L-serine, L-threonine and L-asparagine in a bidirectional way. Provides L-glutamine to proliferating stem and activated cells driving the metabolic switch toward cell differentiation. The transport cycle is usually pH-independent, with the exception of L-glutamate. Transports extracellular L-glutamate coupled to the cotransport of one proton and one sodium ion in exchange for intracellular L-glutamine counter-ion. May provide for L-glutamate uptake in glial cells regulating glutamine/glutamate cycle in the nervous system. Part of transport systems for D-amino acids. Mediates D-serine release from the retinal glia potentially affecting NMDA receptor function in retinal neurons. May contribute to D-serine reabsorption at the brush border of renal proximal tubules thus modulating the dynamics of urinary versus blood D-serine levels. Displays sodium- and amino acid-dependent but uncoupled channel-like anion conductance with a preference SCN(-) >> NO3(-) > I(-) > Cl(-) (By similarity). Through binding of the fusogenic protein syncytin-1/ERVW-1 may mediate trophoblasts syncytialization, the spontaneous fusion of their plasma membranes, an essential process in placental development. (Microbial infection) Acts as a cell surface receptor for Feline endogenous virus RD114. (Microbial infection) Acts as a cell surface receptor for Baboon M7 endogenous virus. (Microbial infection) Acts as a cell surface receptor for type D simian retroviruses.
Synonyms: ASCT2; M7V1; RDRC; AAAT; ATBO; M7VS1; R16
Tractability: Small molecule: a structure with a bound ligand is known. Antibody: UniProt places it where antibodies can reach, with high confidence; its Gene Ontology location is reachable by antibodies, with high confidence; UniProt predicts a signal peptide or a membrane-spanning region; the Human Protein Atlas places it where antibodies can reach. PROTAC: ubiquitination databases record sites on it; its protein half-life has been measured; a small molecule that binds it is known.
Target class: SLC superfamily of solute carriers; SLC06 neurotransmitter transporter family; Electrochemical transporter; Transporter
Gene: Protein-coding gene on chromosome 19 (46,774,883 to 46,788,617, reverse strand). Ensembl gene ENSG00000105281.
Subcellular location: Cell membrane; Apical cell membrane; Melanosome
Subcellular location (Human Protein Atlas): Plasma membrane; Basal body; Centriolar satellite
Pathways (Reactome):
Signal Transduction: RAC1 GTPase cycle; RAC3 GTPase cycle; RHOH GTPase cycle; RHOJ GTPase cycle; RHOQ GTPase cycle
Transport of small molecules: Amino acid transport across the plasma membrane
Gene Ontology:
Molecular function: antiporter activity; L-glutamine transmembrane transporter activity; protein binding; amino acid transmembrane transporter activity; L-aspartate transmembrane transporter activity; neutral L-amino acid transmembrane transporter activity; signaling receptor activity; L-amino acid transmembrane transporter activity; L-serine transmembrane transporter activity; ligand-gated channel activity; symporter activity
Biological process: erythrocyte differentiation; glutamine transport; neutral amino acid transport; protein homotrimerization; amino acid transport; intracellular glutamate homeostasis; L-aspartate import across plasma membrane; L-glutamine import across plasma membrane; transport across blood-brain barrier; amino acid import across plasma membrane; glutamine secretion; L-serine transport
Cellular component: extracellular exosome; membrane; plasma membrane; basal plasma membrane; apical plasma membrane; melanosome
Genetic constraint (gnomAD): Loss-of-function variants: 24 observed, 31.38 expected, observed/expected ratio (o/e) 0.76, 90% interval 0.55 to 1.08. The upper end of that interval is the gene's LOEUF score, 1.08, which puts it in group 4 of 6, group 1 being the genes least tolerant of losing a copy. Missense variants: 634 observed, 691.04 expected, observed/expected ratio (o/e) 0.92, 90% interval 0.86 to 0.98. Synonymous variants: 350 observed, 312.7 expected, observed/expected ratio (o/e) 1.12, 90% interval 1.02 to 1.22.
Homologues: Orthologues: chimpanzee SLC1A5 (99% identical), macaque SLC1A5 (98% identical), dog SLC1A5 (88% identical), pig SLC1A5 (87% identical), mouse Slc1a5 (83% identical), rat Slc1a5 (80% identical), rabbit SLC1A5 (78% identical), guinea pig SLC1A5 (71% identical), tropical clawed frog slc1a5 (67% identical), zebrafish slc1a5 (63% identical). Paralogues in human: SLC1A4 (57% identical), SLC1A3 (41% identical), SLC1A6 (40% identical), SLC1A1 (38% identical), SLC1A2 (38% identical), SLC1A7 (37% identical).
Diseases named in the same sentence as SLC1A5 in open-access papers:
SLC1A5 is named in the same sentence as 140 diseases in open-access papers, as found by Europe PMC text mining. Sharing a sentence is not in itself a finding about the gene and the disease. The quoted sentences say what the papers report.
breast cancer (96 papers, 2011 to 2026). A primary or metastatic malignant neoplasm involving the breast. "They show that SLC1A5 co-expression with Transaldolase 1 (TALDO1) metabolic enzyme in receptor-positive breast cancer cells is associated with failure in endocrine therapy with tamoxifen." (PMID 38705513, 2024). "In MDA-MB-453 and MCF-7 breast cancer cells curcumin caused an increase in SLC1A5 expression, and its silencing prevented glutamine entry reducing curcumin antitumor effects." (PMID 36831394, 2023). "Here, we report that MLN4924, a small-molecule inhibitor of neddylation activating enzyme, increases glutamine uptake in breast cancer cells by causing accumulation of glutamine transporter ASCT2/SLC1A5, via inactivation of CRL3-SPOP E3 ligase." (PMID 35641493, 2022). "To begin investigating the biological co-expression networks associated with SLC1A5 in breast cancer, we used TCSBN database." (PMID 34282517, 2021). "Further analysis on the subgroup of patients who were treated with endocrine therapy alone revealed that SLC1A5 protein expression remained a predictive marker for high risk of breast cancer death (P = 0.03)." (PMID 34282517, 2021). "To further explore specific functions of the identified transcripts associated with SLC1A5 in breast cancer, we performed gene ontology analysis using the Webgestalt tool." (PMID 34282517, 2021). "Taken together, these results suggest increased SLC1A5 transcription and translation associates with aggressive features in luminal breast cancer leading to cancer progression and decreased survival." (PMID 34282517, 2021). "SLC1A5 is associated with breast cancer through various pathways and is an independent prognostic factor for breast cancer, as demonstrated by proteomic profiling analysis." (PMID 29562706, 2018). "SLC1A5 has also been shown to be associated with endocrine resistance in breast cancer cells." (PMID 39852119, 2024). "Interestingly, SLC7A6 and SLC1A5 have been shown to be targets of driver genes implicated in tumorigenesis, such as c-Myc in breast cancer, lung small cell carcinoma, colorectal carcinoma, glioblastoma, and HCC." (PMID 39062801, 2024). "Consistent with that, we found high SLC1A5 expression, as a result of high transcription, is associated with aggressive clinicopathological features and high risk of recurrence in patients with luminal breast cancer." (PMID 34282517, 2021). "Consequently, high SLC1A5 expression in breast cancer revealed a strong association with decreased overall breast cancer survival based on analysis of patient data from GEO database." (PMID 33718214, 2021). "High RNF5 expression and low SLC1A5 expression associate with positive prognosis in breast cancer." (PMID 32296646, 2020). "However, an in vitro study suggested that SLC1A5 might be associated with endocrine therapy failure in some luminal breast cancers." (PMID 39973065, 2025). "Finally, we performed bioinformatics analysis to identify associated networks with SLC1A5 which could have potential roles in response to endocrine treatment in luminal breast cancer." (PMID 34282517, 2021). "Furthermore, SLC1A5 is associated with endocrine resistance in breast cancer cells." (PMID 29562706, 2018). "This indicates that SLC1A5 is crucial for the growth and progression of triple-negative breast cancer, with less impact on luminal breast cancer." (PMID 39973065, 2025). "Multiple studies have indicated that CUR displaysantitumorigenic activity in breast cancer (BC) by inducing ferroptosis, with mechanisms that involve promoting SLC1A5-mediated ferroptosis and inducing HO-1 expression." (PMID 40552277, 2025). "Targeting SLC1A5 to prevent extracellular glutamine uptake and metabolism represents a promising direction for breast cancer therapy." (PMID 39973065, 2025).
breast cancer (continued). "Knockdown of SLC1A5 increased the sensitivity of luminal breast cancer cells to tamoxifen treatment, possibly by modulating the expression of the pentose phosphate pathway enzyme TALDO1, which is crucial for cancer cell growth and proliferation." (PMID 39973065, 2025). "SLC1A5 is significantly overexpressed in most subtypes of breast cancer, but different breast cancer cell lines show varying degrees of dependence on SLC1A5 activity." (PMID 39973065, 2025). "Benzylserine was the first molecule discovered to inhibit SLC1A5 in breast cancer cells, disrupting intracellular glutamine uptake." (PMID 39973065, 2025). "Clinical sample analysis suggested that luminal breast cancer patients with high SLC1A5 expression are more likely to experience relapse after endocrine treatment." (PMID 39973065, 2025). "They found that SLC1A5 was upregulated in endocrine therapy-resistant breast cancer cells, and inhibition of SLC1A5 suppressed the proliferation of breast cancer cells resistant to aromatase inhibitors." (PMID 39973065, 2025). "The same active expression of SLC1A5 ASCT2 was shown earlier when describing luminal subtypes of breast cancer." (PMID 39852119, 2024). "In triple-negative basal-like breast cancer, SLC1A5 inhibition prevents cell proliferation and triggers rapid cell death." (PMID 38705513, 2024). "SLC1A1 is expressed in the luminal subtype of breast cancer, while SLC1A5 is expressed in the HER2-positive subtype." (PMID 39852119, 2024). "Curcumin suppresses breast cancer by elevating solute carrier family one member 5 (SLC1A5) and enhanced glutamine uptake." (PMID 38738174, 2024). "Here, we present evidence that the amino acid transporter ASCT2 (coded by the gene SLC1A5) is a major contributor to serine uptake in luminal/ER+ breast cancer and other tumor cell lines." (PMID 39068660, 2024). "Further investigations revealed that curcumin promotes SLC1A5‐mediated ferroptosis, indicating its potential as a therapeutic agent for breast cancer treatment." (PMID 38140764, 2024). "Many studies have shown that overexpression of SLC1A5 promotes progression in triple-negative basal-like breast cancer 49, prostate cancer 50 and lung cancer." (PMID 38904011, 2024). "SLC1A5, in particular, shown to be upregulated in lung cancer 16, breast cancer 30, head and neck cancer 31, and colorectal cancer." (PMID 39431017, 2024). "Many current studies have shown that SLC1A5 plays an oncogenic role in many cancers, such as hepatocellular carcinoma, lung cancer, breast cancer, and colon cancer." (PMID 37566748, 2023). "It has been demonstrated that high SLC1A5 expression has been correlated with poor prognosis in many cancers, including hepatocellular carcinoma, lung cancer, breast cancer, head and neck squamous cell carcinoma, glioma and pancreatic adenocarcinoma." (PMID 36902506, 2023). "Recent studies have revealed that the SLC1A5 gene is highly expressed in various cancers, including breast cancer, lung cancer, and colorectal cancer." (PMID 37566748, 2023). "When breast cancer cells are exposed to paclitaxel chemotherapies, which induce an ER stress environment, SLC1A5 is ubiquitinated by RNF5 (an important E3 ubiquitin ligase related to ER-stress-related protein regulation)." (PMID 37190313, 2023). "High SLC1A5 expression has been correlated with poor survival in various types of cancer, including hepatocellular carcinoma, lung cancer, breast cancer, colon cancer and head and neck squamous cancer." (PMID 36566214, 2022). "In agreement with our results, breast cancer patients with high expression of RNF5 and low expression of the glutamine transporter SLC1A5 were associated with better prognosis than tumors expressing high SLC1A5 and low RNF5." (PMID 35406574, 2022).
breast cancer (continued). "For example, the overexpression of SLC1A5 facilitates tumor growth through increasing the uptake of glutamine in breast cancer." (PMID 35419359, 2022). "Paclitaxel induction of ER stress in breast cancer cells leads to RNF5 association with and ubiquitination and degradation of SLC1A5/38A2." (PMID 36059650, 2022). "The current study demonstrated that high SLC1A5 expression correlated significantly with a poor prognosis in bladder and breast cancers, renal clear-cell carcinoma, LGG, HCC, mesothelioma, and uveal melanoma." (PMID 34367941, 2021). "Results showed that SLC1A5 expression independently predicted poor prognosis in patients with luminal breast cancer (P < 0.05)." (PMID 34282517, 2021). "In luminal breast cancer, SLC1A5 + TALDO1 + co-expression was predictive of a high recurrence risk and death from breast cancer (P < 0.05)." (PMID 34282517, 2021). "Having determined their correlation with SLC1A5, we next asked which of these genes have a key clinical role in luminal breast cancer and specifically in terms of benefit from endocrine treatment." (PMID 34282517, 2021). "In breast cancer, high expression of SLC1A5 mediates glutamine uptake and sustained cell proliferation." (PMID 34282517, 2021). "In particular, previous data have indicated that SLC1A5 participates in breast cancer progression through regulation of glutamine uptake." (PMID 34738502, 2021). "Next, we performed IHC staining on a large series of samples (n = 1188) for patients with luminal breast cancer to analyze the protein expression of SLC1A5 with clinicopathological features and clinical outcome." (PMID 34282517, 2021). "This database allowed us to explore the relationships between genes and biological functions in breast cancer via the generation of co-expression networks in gene-centric manner (SLC1A5)." (PMID 34282517, 2021). "Using co-expression networks analysis to find potential mechanisms with which SLC1A5 interacts in luminal breast cancer, we identified biological networks of 25 genes that correlated with SLC1A5." (PMID 34282517, 2021). "We first investigated the prognostic value of SLC1A5 mRNA expression in luminal breast cancer patients using METABRIC and KM-Plotter datasets." (PMID 34282517, 2021). "The expression of SLC1A5 is upregulated in breast cancer, colon cancer, lung cancer, melanoma, neuroblastoma, glioblastoma, and prostate cancer." (PMID 34367941, 2021). "In vitro, depletion of SLC1A5 increases the sensitivity of luminal breast cancer cells to tamoxifen." (PMID 34282517, 2021). "Our results using clinical samples showed that patients with luminal breast cancer and high SLC1A5 expression are more likely to relapse after using endocrine therapy." (PMID 34282517, 2021). "Altogether, these findings suggest that SLC1A5 is an emerging key marker of endocrine therapy in luminal breast cancer." (PMID 34282517, 2021). "Relevant literature has reported that SLC1A5 was the most important transporter to absorb exogenous glutamine in various cells (including breast cancer, NSCLC, prostate cancer, etc.), and regulated tumor growth by controlling the cellular entry of glutamine." (PMID 34054543, 2021). "In vitro, this finding was confirmed, where depletion of SLC1A5 in luminal breast cancer cells increased the sensitivity to tamoxifen treatment compared to control cells." (PMID 34282517, 2021). "SLC1A5 expression was assessed at the transcriptomic and proteomic levels in large, well-characterized cohorts of luminal breast cancer." (PMID 34282517, 2021). "In terms of luminal breast cancer previous study reported that low SLC1A5 expression and ER positivity correlated with good prognosis in 119 patients with breast cancer." (PMID 34282517, 2021). "Even though our data demonstrate the prognostic and predictive value of SLC1A5 in luminal breast cancer, the exact mechanisms of how SLC1A5 expression contributes to endocrine resistance still require further mechanistic investigations." (PMID 34282517, 2021).